OR51A4 (olfactory receptor family 51 subfamily A member 4)
Description:
Odorant receptor.
Tractability: Antibody: UniProt places it where antibodies can reach, with medium confidence; UniProt predicts a signal peptide or a membrane-spanning region; its Gene Ontology location is reachable by antibodies, with medium confidence.
Gene: Protein-coding gene on chromosome 11 (4,942,831 to 4,947,605, reverse strand). Ensembl gene ENSG00000205497.
Subcellular location: Cell membrane
Pathways (Reactome):
Sensory Perception: Expression and translocation of olfactory receptors
Gene Ontology:
Molecular function: olfactory receptor activity; G protein-coupled receptor activity; signaling receptor activity
Biological process: cellular response to lipid; detection of chemical stimulus involved in sensory perception of smell; G protein-coupled receptor signaling pathway; system process
Cellular component: plasma membrane; membrane
Genetic constraint (gnomAD): Loss-of-function variants: 1 observed, 0.66 expected, observed/expected ratio (o/e) 1.52, 90% interval 0.32 to 1.92. That is too few expected variants to judge how well the gene tolerates losing a copy. Missense variants: 241 observed, 308.18 expected, observed/expected ratio (o/e) 0.78, 90% interval 0.7 to 0.87. Synonymous variants: 96 observed, 127.22 expected, observed/expected ratio (o/e) 0.75, 90% interval 0.64 to 0.89.
Homologues: Orthologues: macaque OR51A4 (94% identical), dog OR51A4 (88% identical), tropical clawed frog or51ao1 (46% identical). Paralogues in human: OR51A2 (97% identical), OR51A7 (71% identical), OR51G2 (59% identical), OR51G1 (54% identical), OR51L1 (53% identical), OR51Q1 (51% identical), OR51E1 (50% identical), OR51C1 (50% identical), OR51E2 (49% identical), OR51I2 (49% identical), OR51F2 (49% identical), OR51D1 (47% identical), and 39 more.
Diseases named in the same sentence as OR51A4 in open-access papers:
OR51A4 is named in the same sentence as 1 disease in open-access papers, as found by Europe PMC text mining. Sharing a sentence is not in itself a finding about the gene and the disease. The quoted sentences say what the papers report.
cancer (1 paper, 2021). A tumor composed of atypical neoplastic, often pleomorphic cells that invade other tissues. "Among 17 differentially methylated genes in aggressive cases, a few genes, such as SLC17A2 and OR51A4, were not investigated previously for human cancers." (PMID 33450964, 2021).